DPP4 (dipeptidyl peptidase 4)
Diseases named in the same sentence as DPP4 in open-access papers (continued):
Sharing a sentence is not in itself a finding about the gene and the disease.
Hypertension (continued). "GLP-1R agonists and DPP-4 inhibitors could induce natriuresis and relieve hypertension via NHE3 downregulation or increased BNP release." (PMID 33923115, 2021). "The present study was undertaken to test our hypothesis that linagliptin, a DPP-4 inhibitor, administration initiated after onset of hypertension and cardiac hypertrophy can ameliorate cardiovascular injury in Dahl salt-sensitive hypertensive rats (DS rats)." (PMID 25471116, 2014). "Thus, the effect of DPP-4 inhibition on blood pressure appears to be dependent on type of hypertension or experimental conditions." (PMID 25471116, 2014). "More studies will need to be done to elucidate the effects of DPP-4 inhibition on hypertension." (PMID 23710467, 2013). "Interestingly, a growing body of research has discovered that DPP-4 inhibitors might prevent a range of cardiovascular conditions, including HF, coronary atherosclerosis, calcified aortic valve disease, and hypertension." (PMID 40429343, 2025). "The crude HR (SGLT2 vs DPP-4 inhibitors as a reference group) was 0.88 (0.76–1.02) and the aHR in model 3 (based on an inverse probability weighting of propensity score calculated from age, sex, year, and drugs for hypertension, dyslipidemia, and hyperuricemia) was 0.94 (0.80–1.11)." (PMID 41041642, 2025). "A growing body of research indicates that DPP4 inhibitors may be beneficial in treating a number of cardiovascular conditions, such as HF, coronary atherosclerosis, calcified aortic valve disease, and hypertension." (PMID 40429343, 2025). "It should be kept in mind that IR is often associated with abnormal lipid metabolism and hypertension, and those two traditional CV risk factors may explain the increase in AS in T2DM and MS as well as the potential benefit of DPP-4 inhibition derived therapies." (PMID 27006706, 2016). "The main purpose of this work was to determine whether initiation of DPP-4 inhibitor linagliptin administration after onset of hypertension and cardiac hypertrophy can exert direct beneficial effects on cardiovascular injury induced by salt-sensitive hypertension." (PMID 25471116, 2014). "GRAPPLE suggests pathways from DPP4 gene expression at the mRNA level to MI and stroke are notably influenced by factors such as BMI, SLC4A10, total cholesterol (TC), hypertension (HTN), and total triglyceride (TG)." (PMID 40904650, 2025). "Conversely, the proportions of hypertension, hyperlipidemia, CHF, cerebrovascular disease, and CKD were higher in the DPP4 inhibitor user group." (PMID 38110464, 2023). "Hypertension was the most common comorbidity in the enrolled population; after propensity score weighting, 22 369 patients (84.20%) in the DPP-4 inhibitor group and 506 (83.92%) in the GLP-1 receptor agonist group had hypertension." (PMID 35254430, 2022). "As both hypertension and T2DM are increasing global threats to human health, a lot of research has been focused on finding inhibitors for ACE or DPP4." (PMID 36360120, 2022). "In brief, patients with hypertension can be more prone to RAS imbalance, which in turn lead to vasoconstriction/inflammation due to unopposed Ang II effect, aggravated by increased DPP4 vascular activity/expression and by chronic low-grade inflammation." (PMID 33329052, 2020). "Investigating the regulatory activity of DPP-4 upon the inflammatory mediators and oxidative stress associated with elevated BP may provide us with good expectations for the future use of DPP-4i in the treatment of hypertension, especially in patients with inflammation." (PMID 31134095, 2019). "This case report describes the effect of vildagliptin, a dipeptidyl peptidase-4 (DPP-4) inhibitor, on the central SBP in a 54-year-old woman with hypertension and DM." (PMID 26166078, 2015). "There is no established direct relationship between hypertension and DPP4 activity, however, a link is suggested as there is a context-dependent impact of DPP4 inhibitors on blood pressure." (PMID 39507187, 2024).
Hypertension (continued). "Our study provides evidence of renoprotection by DPP4 inhibition in a nondiabetic hypertension-induced model of chronic cardiorenal syndrome, indicating that DPP4 pathway remains a valid object to study in the context of chronic multiorgan diseases." (PMID 30774748, 2019). "This study provides evidence that DPP4 inhibition exerts renoprotective effects through anti-inflammatory actions in a nondiabetic, hypertension-induced model of cardiorenal syndrome." (PMID 30774748, 2019). "The corresponding ORs for high blood pressure, high TG, low HDL cholesterol, high WHR and high urine ACR according to baseline DPP4 activity were 3.66, 2.30, 2.84, 2.53 and 1.90, according to baseline active GLP-1 were 0.51, 0.19, 0.29, 0.38 and 1.10 respectively." (PMID 24647445, 2014). "Hence, a natural bioactive peptide with both DPP4 and ACE inhibitory activities may be helpful in treating or slowing down complications in diabetes and hypertension." (PMID 39595018, 2024). "Furthermore, GLP-1 analogues and DPP-4 inhibitors have been shown to reduce BP (prior to reduction of body weight) in diabetic and non-diabetic patients with hypertension." (PMID 23844037, 2013). "Moreover, the effectiveness of T2DM drugs, including metformin, sulfonylureas, dipeptidyl peptidase 4 (DPP-4) and sodium-glucose transport protein 2 (SGLT-2) inhibitors, may vary between individuals due to several factors including heredity, age, gender, hypertension and others." (PMID 40775340, 2025).
atherosclerosis (88 papers, 2010 to 2025). A disease characterized by the build-up of fatty material and calcium deposition in the arterial wall resulting in partial or complete occlusion of the arterial lumen. "In this study, we reported a previously unrecognized role of DPP4 in atherosclerosis associated inflammation though regulation of T‐cell migration via Mid1, a microtubule‐associated protein." (PMID 36683148, 2023). "In the present study, associations were demonstrated between DM, FBG, DPP-4-inhibitor use, and atherosclerosis." (PMID 35893426, 2022). "It has been reported that the polymorphisms of DPP‐4 were associated with the risk of myocardial infarction in patients with atherosclerosis." (PMID 32713161, 2020). "We aimed to review the evidences that reinforce the associations between DPP4, atherosclerosis, and T2DM." (PMID 26146634, 2015). "In this way, it has been demonstrated that DPP4 is a new adipokine associated with increased visceral obesity, IR, and metabolic syndrome, which is consistent with its possible link with atherosclerosis." (PMID 26146634, 2015). "Moreover, DPP4 protein abundance was also elevated in aged human, mouse, and monkey aortic tissue, suggesting that DPP4 increases in atherosclerosis, conditions often associated with increased senescent cells." (PMID 37097759, 2023). "To test if T‐cell specific deficiency of DPP4 may reduce atherosclerosis, we adoptively transferred Dpp4+/+ or Dpp4−/− pan T cells into lymphocyte deficient Rag1−/− mice in order to generate T‐cell specific DPP4 deficient chimeric mice." (PMID 36683148, 2023). "Given that DPP4 levels and activity increase with hVSMC senescence, we asked whether DPP4 is elevated in atherosclerosis, a disease in which senescent VSMCs have been implicated." (PMID 37097759, 2023). "Cross-talk between advanced glycation end products (AGE) and their receptors (RAGE) with the dipeptidyl peptidase-4 (DPP-4)-incretin system has been implicated in the pathogenesis of a number of diabetic complications, including retinopathy, nephropathy, and atherosclerosis." (PMID 28962617, 2017). "Molecular and biochemical effects of GLP-1 RAs and DPP-4 inhibitors influencing cardiovascular health in studies related to atherosclerosis and coronary artery disease." (PMID 40725024, 2025). "DPP4 improved atherosclerosis formation in mice by inhibiting oxidative stress and can also alleviate atherosclerosis by promoting M2 macrophage polarization." (PMID 40894479, 2025). "GLP-1RA supplementation and DPP-4 inhibition improve vascular function in animal models of atherosclerosis by reducing inflammation and oxidative stress." (PMID 40803202, 2025). "Fortunately, research on animals and in humans has shown that DPP-4 inhibitors can prevent atherosclerosis." (PMID 40429343, 2025). "Dipeptidyl peptidase-4 (DPP-4) inhibitors have shown favorable pleiotropic effects on atherosclerosis to improve endothelial cell function, which is essential for maintaining vascular integrity and preventing atherosclerotic progression." (PMID 40649729, 2025). "DPP4 plays a role in regulating glucose metabolism, lipid processing, and inflammation, thereby potentially contributing to the progression of atherosclerosis." (PMID 40249657, 2025). "The promising results with GLP-1RA and DPP-4 inhibition in endotoxemia and atherosclerosis models support their potent anti-inflammatory effects." (PMID 40803202, 2025). "In summary, this study identified a previously unrecognized role of DPP4 in regulating T‐cell migration and atherosclerosis." (PMID 36683148, 2023). "Dipeptidyl peptidase 4 (DPP4) is identified as a crucial molecule promoting T‐cell migration in atherosclerosis via midline‐1‐dependent cytoskeletal rearrangement." (PMID 36683148, 2023). "In particular, given the obligatory role of T cells in atherosclerosis and the high levels of DPP4 expression in T cells, the role of T‐cell derived DPP4 in vascular inflammation and atherosclerosis deserves investigation in detail." (PMID 36683148, 2023).
atherosclerosis (continued). "Here, this work demonstrates that dipeptidyl peptidase‐4 (DPP4) is a novel regulator of T‐cell motility in atherosclerosis." (PMID 36683148, 2023). "In light of the increase in DPP4 levels and activity in senescent hVSMCs and confirmed in various models of atherosclerosis, we sought to understand the role of DPP4 on senescent hVSMCs." (PMID 37097759, 2023). "Future studies using cell‐specific DPP4 knockout models will be necessary to examine the role of DPP4 in other types of cells and atherosclerosis." (PMID 36683148, 2023). "Collectively, we demonstrate that T‐cell derived DPP4 plays an important role in atherosclerosis by regulating Mid1‐mediated migration." (PMID 36683148, 2023). "In animal models, gliptins have the ability to reduce atherosclerosis and inflammation independently of the canonical role of DPP4 in glucose metabolism." (PMID 37097759, 2023). "DPP4 controls T‐cell migration by regulating Mid1‐dependent cytoskeletal rearrangement, and thus promotes vascular inflammation in atherosclerosis." (PMID 36683148, 2023). "We sought to recapitulate previous studies in which DPP4 inhibitors were effective at reducing atherosclerosis and inflammation in mice." (PMID 37097759, 2023). "DPP4 inhibitors play a direct role in anti-atherosclerosis by improving endothelial dysfunction, inhibiting inflammation and oxidative stress, and improving plaque instability." (PMID 35630534, 2022). "Treatment of senescence-related chronic disease, as shown by recent studies with DPP4 inhibitors that ameliorated atherosclerosis in type 2 DM patients, prevented vascular aging and protected chondrocytes from TNF-α-induced senescence." (PMID 35251476, 2022). "The clinical data also showed a positive and significant correlation (r = 0.458, p < 0.01; r = 0.427, p < 0.05; r = 0.430, p < 0.01; r = 0.330, p < 0.05) between atherosclerosis, DM, DPP-4 inhibitors users, and FBG, respectively." (PMID 35893426, 2022). "High levels of soluble DPP4 are found in atherosclerosis and many studies have shown that its inhibition results in restrained atherosclerosis progression." (PMID 33440821, 2021). "Recently, DPP-4 inhibitors have been shown to play a protective role against atherosclerosis in diabetic animal models and T2D patients." (PMID 32646003, 2020). "Several experimental studies have shown that DPP-4 inhibitors can inhibit foam cell formation and atherosclerosis in both GLP-1-dependent and GLP-1-independent manners." (PMID 29402270, 2018). "We previously demonstrated in in vivo studies that GLP-1, GIP, and a DPP-4 inhibitor, respectively, prevented the acceleration of atherosclerosis via suppression of foam cell formation regulated by CD36 and ACAT-1 in macrophages isolated from mice." (PMID 30627161, 2018). "Gliptins are inhibitors of the dipeptidyl peptidase-4 (DPP4) enzyme and have demonstrated a vasoprotective and vasoregenerative impact after endothelial injury and during early atherosclerosis." (PMID 29531541, 2018). "Many previous studies have provided the evidences that incretin-related agents such as GLP-1 analogues and DPP-4 inhibitors provide beneficial effects against atherosclerosis." (PMID 29402270, 2018).
atherosclerosis (continued). "Application of newly developed DPP4 inhibitors revealed several physiological and pathological processes such as lipid metabolism, myocardial, renal and liver functions, atherosclerosis and inflammation in which DPP4 is involved." (PMID 29472575, 2018). "In the current review, we will summarize the recent advances in direct and indirect regulatory role of DPP4 in atherosclerosis." (PMID 28619058, 2017). "Improvement of atherosclerosis by DPP-4 inhibition presumably due to inhibition of monocyte activation/chemotaxis has been reported." (PMID 28118775, 2017). "In the current review, we will summarize the recent advances in direct and indirect regulatory role of DPP4 in cardiovascular disease, especially in atherosclerosis." (PMID 28619058, 2017). "Dipeptidyl peptidase-4 (DPP4) is one of the most potent mammalian serine proteases participated in the pathogenesis of subclinical atherosclerosis." (PMID 27654253, 2016). "There are published experimental data showing that incretin therapy, including treatment with GLP-1 analogues or DPP-4 inhibitors, attenuates atherosclerosis." (PMID 27351380, 2016). "The vascular anti-fibrotic role of DPP-4 inhibitors has been reported previously in models of atherosclerosis and neo-intima injury." (PMID 27391040, 2016). "In vivo studies have revealed that the administration of GLP-1 analogues or DPP-4 inhibitors reduces high-fat-diet-induced atherosclerosis and stabilizes plaques in apoE knockout mice." (PMID 27351380, 2016). "Another study reported improvement of both hyperglycemia and atherosclerosis after a long-term treatment with the DPP-4 inhibitor alogliptin." (PMID 25785279, 2015). "Taken together, these evidences suggest the existence of a pathophysiological interaction between DPP4, endothelial dysfunction, and inflammation, factors that are directly linked to the pathogenesis and clinical manifestations of T2DM and atherosclerosis." (PMID 26146634, 2015). "GLP-1 supplementation and DPP-4 inhibition induce protective effects on vascular function in animal models of atherosclerosis." (PMID 26251902, 2015). "There is good evidence that DPP4 inhibition mediates protective effect on myocardial infarction, hypertension, and atherosclerosis." (PMID 26075284, 2015). "They demonstrated nicely the reduction of chemotaxis and monocyte activation by DPP-4 inhibitor therapy in both models of atherosclerosis." (PMID 26251902, 2015). "Sitagliptin, as one of the DPP-4 inhibitors, has been reported to play a protective role in the cardiovascular disease included atherosclerosis." (PMID 24490809, 2014). "The present study confirmed our previous observation by showing once again that a DPP-4 inhibitor significantly suppressed the development of atherosclerosis in Apoe−/− mice fed an atherogenic diet." (PMID 23967137, 2013). "Yet the mechanism by which DPP-4 inhibitors suppress the development of atherosclerosis has yet to be fully elucidated." (PMID 23967137, 2013). "Several recent reports have revealed that dipeptidyl peptidase (DPP)-4 inhibitors have suppressive effects on atherosclerosis in apolipoprotein E-null (Apoe−/−) mice." (PMID 23967137, 2013). "In addition to lipid regulation, DPP-4 inhibitors exert significant anti-inflammatory and antioxidant effects, thereby attenuating key contributors to atherosclerosis." (PMID 40649729, 2025). "On the other hand, DPP-4 inhibitor may induce endothelial cell proliferation in the glomerulus, which may lead to pathological conditions other than atherosclerosis." (PMID 38055184, 2024). "In conclusion, we identified the targets of ferroptosis in atherosclerosis associated with garlic, including GPX4, DPP4 and ALOX5, providing new mechanistic insights that may be clinically relevant for combination therapies of garlic." (PMID 39108744, 2024).